CXCR6 (C-X-C motif chemokine receptor 6)
Diseases named in the same sentence as CXCR6 in open-access papers (continued):
Sharing a sentence is not in itself a finding about the gene and the disease.
tumor (continued). "High expression of CXCL16 and CXCR6 promoted HCC invasiveness and a pro-tumor inflammatory environment caused by the recruitment of neutrophils." (PMID 31991677, 2020). "Although ELR− CXC chemokines belong to the antiangiogenic CXC chemokine family, ELR− CXC chemokines, including CXCR3, CXCR4, CXCR5, CXCR6, and CXCR7, are associated with tumor growth, proliferation, and metastasis in PC." (PMID 33195424, 2020). "Oral administration of vancomycin altered gut commensal bacteria in mice, increasing CXCL16 expression of liver sinusoidal endothelial cells, thus recruiting hepatic CXCR6+ NKT cells that exert anti-tumor effect." (PMID 31991677, 2020). "Of these, interleukin‐1β (IL‐1β) showed age‐dependent upregulation in control lungs and tumors from old mice, whereas tumor‐specific upregulation was observed for Ccl7, IL‐15ra, and Cxcr6 cytokines in old mice." (PMID 29047229, 2018). "Using cxcr6ko mice, we confirmed the crucial role of the CXCL16/CXCR6 axis in the establishment of a pro-tumor microenvironment." (PMID 30542347, 2018). "All these data indicate that activation of CXCL16/CXCR6 axis in human primary GBM cells is able to promote tumor cell proliferation, migration and invasion." (PMID 30542347, 2018). "In UC specimens, CXCR6 expression was consistently intermediately or strongly expressed in tumour cells and infiltrating inflammatory cells." (PMID 29285224, 2017). "Another study on hepatocellular carcinoma indicated importance of CXCL16 and its receptor CXCR6 in neutrophil recruitment and tumor progression due to its ability to stimulate the release of CXCL8 by tumor cells." (PMID 29340117, 2017). "αSMA expression on the tumour-recruited CXCR6+ stromal cells was also identified as an attribute responsible for their stimulatory effect on cancer progression." (PMID 27241286, 2016). "Stimulation of tumor cells via CXCR6 induces the production of CXCL8 which induces the recruitment of neutrophils." (PMID 27618112, 2016). "Other studies have found that TGF-β and SDF-α cytokines as well as CXCR6 are important mediators of the migration of BM-MSCs to the tumor microenvironment." (PMID 27782859, 2016). "Recent study on hepatocellular carcinoma indicated importance of CXCL16 and its receptor CXCR6 in neutrophil recruitment and tumor progression, due to its ability to stimulate tumor cells to release CXCL8." (PMID 26648665, 2015). "CXCR6+ cells resulted in larger tumour mass in a significantly shorter time period, as compared to unsorted cells." (PMID 27429260, 2014). "Our group demonstrated in a poorly immunogenic mouse carcinoma that radiation-induced up-regulation of the chemokine CXCL16 was required for the efficient recruitment to the tumor of CXCR6+ effector CD8 T cells, resulting in optimal tumor inhibition." (PMID 22937524, 2012). "Actually, CXCR6+ cells resulted in larger tumor mass in a signficantly shorter time period, as compared to unsorted cells." (PMID 21203549, 2010). "Taken together, our data suggest that CXCL16 and CXCR6 may mark cancers arising in an inflammatory milieu and mediate pro-tumorigenic effects of inflammation through direct effects on cancer cell growth and by inducing the migration and proliferation of tumor-associated leukocytes." (PMID 19690611, 2009). "The CXCL16 receptor, CXCR6, has been reported to be expressed on Th1 cells, on tumor infiltrating lymphocytes, and on a variety of leukocytes in inflamed tissue sites, and can serve as a co-receptor for HIV-1." (PMID 19690611, 2009). "Our study is the first to describe expression of the chemokine CXCL16 and its receptor CXCR6 on both cancer cells and adjacent T cells in human cancer and demonstrate correlations between expression of CXCL16 and CXCR6 and tumor progression." (PMID 19690611, 2009). "Our data suggest possible direct effects of CXCL16/CXCR6 on cancer cell growth and thereby on tumor development." (PMID 19690611, 2009).
tumor (continued). "To validate the hypothesis that tumor cells recruit Tc17 cells via the CXCL16-CXCR6 axis, we categorized spots with tumor cells into CXCL16+ and CXCL16- groups and compared the expression of CXCR6 in surrounding Tc17 cells." (PMID 40452847, 2025). "mregDC is the cell state with the highest expression of CXCL16 (the ligand for CXCR6), CXCR6 is the most highly expressed chemokine receptor on tumor-infiltrating CTLs, and mregDCs can also express and transpresent the survival factor IL-15, which supports CTL survival." (PMID 41430039, 2025). "The CXCR6/CXCL16 axis is crucial for TRM cell retention in tumours." (PMID 40361472, 2025). "Moreover, the genes related to T cell activation, such as Pdcd1, Cxcr6, Gzma, Gzmb, and Prf1, also upregulated in the tumor of αmPD1-IL-2x and mAWT020 treated mice." (PMID 40046051, 2025). "CXCL16 facilitate tumor cell migration by interacting with its receptor CXCR6." (PMID 39995663, 2025). "Importantly, inhibition of either VEGFA or the PI3K/AKT/mTOR pathway reversed the increased migratory and invasive abilities of CRCs following CXCR6 silencing, highlighting the receptor’s key role in regulating tumor aggressiveness." (PMID 40943634, 2025). "Furthermore, the disruption of certain chemokine receptors, such as CXCR6 and CXCR16, has been associated with a reduction in tumor metastasis." (PMID 40066223, 2025). "Notably, CXCR6 expression was markedly upregulated in both circulating and tumor-infiltrating CD8+ MAIT cells from responders." (PMID 41149503, 2025). "Moreover, mature FOXP3+ Tregs in the tumor express CXCR6, IL21R, IL1R1, IL18R1, and, to a lesser extent, CCR8." (PMID 40164596, 2025). "However, owing to the limited number of samples, only the expression of CXCR6 on T cells in non-tumor tissues was significantly higher than that in circulating T cells." (PMID 38335302, 2024). "Furthermore, anti-tumor immunity-related pathways were significantly enriched in the CXCR6 high-expression group, suggesting that CXCR6 upregulation enhanced immune surveillance and suppressed tumor progression." (PMID 39588301, 2024). "Importantly, we demonstrated that CXCR6 was predominantly expressed in T and NK cells and played a pivotal role in mediating anti-tumor immunity through interactions with CXCL16+ macrophages and DC." (PMID 39588301, 2024). "Notably, CXCR6 is crucial for the long-term tumor control mediated by CD8+ cytotoxic T lymphocytes within the tumor microenvironment." (PMID 39588301, 2024). "Although we focused on the CXCL16/CXCR6 axis as a potential mechanism for T cell blockade at tumor margins, proposing the disruption of this axis by blocking glycolysis in CXCL16+ glyCAF54,55, future studies may delve into more targeted interventions." (PMID 38509063, 2024). "Evidence has shown that these cells can exhibit a pro-tumorigenic role, attributed to excessive production of certain cytokines associated with tumor progression (e.g., IL-8 in the case of MAIT) or increased fibrogenesis (e.g., potentiated by iNKT-secreted CXCR6)." (PMID 38774646, 2024). "Importantly, CXCL16+ macrophages and dendritic cells recruited CXCR6+ T and NK cells, which exhibited enhanced cytotoxicity, thereby amplifying anti-tumor immunity." (PMID 39588301, 2024). "Then, we assessed if Cxcr6−/− T cells exhibit increased infiltration into the tumor mass in vivo." (PMID 38509063, 2024). "Furthermore, CXCR6 acts as an exclusive marker for tumor-specific memory CD8+ T cells residing within the tumor rather than circulating in the bloodstream." (PMID 38903506, 2024). "In addition to CSF1 and IL-4-mediated TAM reprogramming, the chemokine CXCL16 released from tumor cells has also been shown to bind to CXCR6 on microglia cells and drive them toward a pro-tumor phenotype." (PMID 38254796, 2024).
tumor (continued). "In cancer studies, CXCR6 (C-X-C Motif Chemokine Receptor 6) plays an important role in regulating effector and regulatory T cell recruitment into tumor tissues, thus enabling targeted therapy that promotes local anti-tumor immunity." (PMID 37593098, 2023). "Knowing how the CXCL16/CXCR6 axis is expressed by myeloid cells and T cells in tumors, the next step was to understand how this axis influences the composition of immune cell populations in the tumor microenvironment." (PMID 38299146, 2023). "Additionally, the combination of αTIGIT with lenalidomide increased CXCR6 gene expression in cytotoxic T cells, which putatively positions these cells to interact with dendritic cells in the tumor microenvironment that provides critical survival signals." (PMID 36512425, 2023). "First, the sample size was limited, and larger cohorts of data are needed to generalize our findings and investigate how additional factors, such as tumor sites, tumor grade and disease subtypes, may be associated with CD8+CXCR6+ T cell subsets." (PMID 37593098, 2023). "Additionally, we assessed the significance of CXCR6 expression in T-cell activation and the initial migration to tumor tissues." (PMID 38299146, 2023). "Expressed on CD8+ T, NK, and CD4+ T cells, CXCR6 could promote the recruitment of tumor-infiltrating lymphocytes in combination with CXCL16 expressed by tumor cells, thus contributing to a better prognosis for cancer patients." (PMID 35978426, 2022). "However, anti-PD-L1 treatment resulted in upregulation or downregulation of numerous genes in CD45+ tumor-infiltrating immune cells in TCh3 tumors, including Cd3d, Cd3e, Cd3g, Cd8a, Cd8b1, Nkg7, Ccl5, Ets1, Icos, Cxcr6, Pdcd1, Lag3, Prf1, and Gzmb (right)." (PMID 35366939, 2022). "Further, the authors speculate that CXCR6-dependent retention of trNK cells in hepatic sinusoids likely explains their critical role in regulating tumor cell seeding." (PMID 36733396, 2022). "Compared with peritumor tissues, CXCR6+TAMs infiltrated more in tumor tissues." (PMID 36230570, 2022). "In this article, we first reported that CXCR6 was expressed by macrophages in CC, which could also be positively related to tumor progression, thus predicting a worse prognosis." (PMID 36230570, 2022). "Therefore, in this review, we decided to restrict our focus on the role of CXCR6 expressed by T cells in a tumor context." (PMID 36311728, 2022). "In a functional level, CXCR6 is critically involved in TRM retention in the primary tumor." (PMID 36305904, 2022). "CXCR6 up-regulation immediately precedes or accompanies loss of TCF-1 expression in tumor-reactive PD-1+ CD8+T cells, whose specificity is infered by the expression of PD1, a marker enriched within anti-tumor T cells." (PMID 36311728, 2022). "CXCR6+TAMs may play a pivotal role in suppressing tumor immunity by suppressing the activation of CD8+ T cells." (PMID 36230570, 2022). "To investigate whether A. muciniphila excert anti-tumor through NKT cell activation, we used CD1d-knockout mice (which completely lack NKT cells) and CXCR6-knockout mice (which have a selective NKT deficiency in the liver)." (PMID 36531991, 2022). "Since we find that the PD-1 tumor-infiltrating NK cells are expressed primarily in the CXCR6+ NK cell population, this may open up new possiblities to investigate the function of NK cells in the setting of PD-1/PD-L1 therapy." (PMID 36185379, 2022). "The infiltration of CXCR6+TAMs was higher in tumor tissues and increased with advanced tumor stage." (PMID 36230570, 2022). "Thus, the use of CXCR6-transduced CD8 T cells in pancreatic tumor-bearing mice allows their migration in the tumor where they can play their antitumor role." (PMID 36429101, 2022). "Cxcr6 deficiency in mice neither affects TCF1+CD8+ T cells in lymph node or tumor microenvironment (TME), nor the CX3CR1 population in lymph nodes." (PMID 36311728, 2022).
tumor (continued). "Although the frequency of PD-1-expressing tumor infiltrating CD62L+CXCR6- NK cells was low (1.5%±0.7 n = 9), PD-1 expression was associated with the CD62L−CXCR6+ NK cells, with approximately 25% of tumor infiltrating CXCR6+ NK cells expressing PD-1 (29% ± 11 n = 9)." (PMID 36185379, 2022). "However, this recruitment is usually matched by an egress of Trm cells out of the tumour to the draining lymph nodes which is accompanied by decreased expression CXCR6." (PMID 36562609, 2022). "Targeting MSCs and CXCL16/CXCR6 signalling to prevent the tumour recruitment of MSCs may be a novel effective therapeutic strategy for combating tumour metastasis." (PMID 35869057, 2022). "Furthermore, patients with HCC had lower peritumoral CXCR6 expressing lymphocytes compared to cirrhosis, which taken together suggests a tumor surveillance function of NKT cells in the liver." (PMID 33578800, 2021). "In addition, the increase in hepatic PD1+CXCR6+CD8+ T cells during NASH-HCC progression impairs anti-tumor immunotherapy against HCC." (PMID 34681695, 2021). "Furthermore, in a snapshot of TCR repertoire analysis, more tumor CXCR6− TEff/EM TCRs overlapped with TRMs isolated from the distant mucosa than CXCR6+ TEff/EMs in the tumor." (PMID 33979626, 2021). "Furthermore, CXCL16 is highly produced by tumor cells and CXCR6− TEff/EMs are the major subset preferentially egressing the tumor to form distant TRMs." (PMID 33979626, 2021). "KO of CXCR6 in tumor-specific T cells enhanced their responses in blood and spleen." (PMID 34607898, 2021). "In addition, we found that both CXCR6−IL7R+IL18R1+ and CXCR6+PD-1+ subsets shared TCR clonotypes with tumor TRMs." (PMID 33979626, 2021). "Interestingly, activation of the SDF-1 CXCR4 axis results in tumor mediated secretion of CXCL16 to recruit CXCR6 positive mesenchymal stem cells to the tumor microenvironment." (PMID 34503118, 2021). "Although higher levels of TILs could be regarded as a favorable prognostic sign, the high expression of CXCL16 in tumor tissues accompanying increasing it self's expression of CXCR6 might effectively interrupted the antitumor immune process." (PMID 34345211, 2021). "Furthermore, increased infiltration of CD8+ T cells expressing the chemokine receptor CXCR6—which is the receptor for CXCL16—was observed in the tumor tissues treated with iPS-ML-41BBL compared to those treated with iPS-ML." (PMID 33669419, 2021). "CCR5, CCR2, CXCR3, and CXCR6 were highly expressed by both tumor Tconv and Treg." (PMID 34868991, 2021). "For, tumor CXCL16/CXCR6 axis might dominantly consume the large portion of CXCL16 and promote self-reproduction and migration, less CXCL16 would be released out to recruit the CXCR6+ T cells, which might be a distinct tumor escape mechanism in GC." (PMID 34345211, 2021). "While CXCR6-deficient CD8 effector T cells were capable of infiltrating primary tumors, CD8 TRM cell positioning within MAV-affected skin was disrupted, resulting in defective anti-tumor memory responses." (PMID 34362825, 2021). "A cleavable antibody specifically targeting mesothelin+ tumor cells and containing the chemoattractant CXCL16, which binds CXCR6, improved NK cell infiltration after adoptive transfer, which reduced tumor burden and prolonged survival in orthotopic or metastatic PDA murine models." (PMID 33584701, 2020). "Moreover, analysis of Iba1 and CD68 immune-reactivity within the tumor mass reveals a different activation state of GAMs in cxcr6ko mice, indicating an effect of CXCR6 signaling on GAMs activation." (PMID 30542347, 2018). "Mice injected with tumor cells silenced for CXCR6 revealed a significant reduction (67%) in tumor volume compared to mice injected with GL261 expressing CXCR6 (2.19 ± 0.47 mm3 shCXCR6 + IPTG mice vs. 6.54 ± 1.26 mm3 shCXCR6–IPTG) (n = 5, p < 0.05; Student's t-test)." (PMID 30542347, 2018).
tumor (continued). "Within these tumors, the CXCL16/CXCR6 axis plays a multifaceted role by promoting proliferation and migration of tumor cells and attraction and modulation of immune cells supporting immune-mediated tumor control." (PMID 28698473, 2017). "In order to distinguish adoptive and endogenous CTLs by intravital imaging, the adoptive CTLs were labeled with the red fluorescent dye CMTPX and then transferred into Cxcr6+/gfp transgenic mice with CFP-B16 tumor cells implanted into the window chamber on Day 0 (six days after tumor implantation)." (PMID 27855783, 2016). "Similarly, we have shown that CXCR6−/− mice, which have significantly reduced numbers of iNKT cells in the liver and lung, are protected from tumor metastasis by glycolipid treatments." (PMID 27471636, 2016). "Quantitative analysis confirms that CXCR6 expression is increased in tumor." (PMID 25909173, 2015). "To further evaluate whether CXCR6 induces tumor metastasis in vivo, we transplanted MDA-231-lucCXCR6/shCXCR6-2# and respective MDA-231-lucCXCR6/shCtrl cells tagged with luciferase into nude balb/c mice by tail vein injection." (PMID 25909173, 2015). "In addition, CCR6/CCL20 interaction in endometrial adenocarcinoma, CXCR1/2/CXCL7 interaction in clear cell renal cell carcinoma, CXCR2/CXCL8 interaction in nasopharyngeal carcinoma, and CXCR6/CXCR16 interaction in HCC are reported to promote tumor cell growth." (PMID 25110692, 2014). "CXCL16 and CXCR6 levels increase as tumor malignancy increases in some literatures." (PMID 23941552, 2013). "Furthermore, in the CXCR6+ IGR37 tumor xenograft, all the MAA family proteins overlapped with the exception of CXCR6+ IGR37 cells for tyrosinase, Mart-1, and Gp100." (PMID 21203549, 2010). "CXCL16 could enhance tumor growth directly through CXCR6-mediated effects on the proliferation/survival of cancer cells and indirectly through enhanced recruitment and proliferation/survival of cytokine-producing T cells." (PMID 19690611, 2009). "Notably, CXCL16 (a ligand) from tumor cells and CXCR6 (a receptor) on HLA-DR+CD38+CD8+ T cells—previously implicated in enhancing anti-PD-1 therapy efficacy in other cancers—may mediate key tumor‒immune interactions." (PMID 41565617, 2026). "Additionally, CXCL16 or CXCR6 signaling can directly support tumor progression and invasion." (PMID 41157253, 2025). "Moreover, CXCR6 expression decreased with advancing tumor stage." (PMID 39588301, 2024). "Histological analysis of Ccne1-SIIN tumors showed an increased accumulation of transferred CXCR6-deficient OT-1 T cells in the tumor parenchyma relative to wildtype T cells, suggesting that releasing CD8+ T cells from CXCL16-CXCR6 mediated retention at the tumor margin can reverse T-cell exclusion." (PMID 38509063, 2024). "Our analyses showed that CD8+ T cells, which are directly associated with tumor immunotherapy response, as well as T cells were more highly expressed at higher levels of all four molecules; B cells were also more highly expressed at higher levels of XCR1, CCR10, CXCL13, CXCR6." (PMID 39835121, 2024). "Notably, CXCR6+ CD8 T cells were characterized as tumor enriched cells that may be potential predictors of high immune infiltration and the immune-checkpoint blockade response, and may serve as therapeutic targets." (PMID 37593098, 2023). "In addition, CXCR6 is upregulated during the conversion of memory stem-like into effector-like CTLs and represents an immune checkpoint determining the magnitudes and outcomes of anti-tumor immune responses." (PMID 37593098, 2023). "But the function of CXCR6+TAMs in the tumor immune microenvironment is still unknown." (PMID 36230570, 2022). "Furthermore, administration of anti-PD-1 antibody increased CD8+ PD-1+ CXCR6+ T cells in the tumor." (PMID 35565198, 2022). "Thus, CXCR6 is involved in immune response to tumor, infection and allograft rejection." (PMID 35058922, 2021).